KRAS (KRas proto-oncogene, GTPase)
Diseases named in the same sentence as KRAS in open-access papers (continued):
Sharing a sentence is not in itself a finding about the gene and the disease.
pancreatic cancer (continued). "In addition to the KRAS mutation as therapeutic target for RNAi, other genes such as protein kinase N3 have been investigated as targets for siRNA in pancreatic cancer." (PMID 34683931, 2021). "In pancreatic cancer, KRAS mutations are present in 90% of cases." (PMID 34113570, 2021). "KRAS mutations occur at all stages from pancreatic intraepithelial neoplasia (PanINs) to invasive and metastatic disease and can be observed in more than 90% of pancreatic cancer patients." (PMID 34540683, 2021). "Our observation, combined by findings from other groups, corroborates the hypothesis that detection of ctDNA mutated KRAS at diagnosis of advanced pancreatic cancer is correlated with reduced time-to-progression and overall survival." (PMID 35083150, 2021). "Finally, we sought to investigate phosphorylation of endogenous KRAS in a human pancreatic cancer cell line with KRAS Q61H mutation (Hs766T)." (PMID 34725361, 2021). "Pancreatic cancer with activating mutations in KRAS or BRAF occur frequently, and oncogenic pathways like RAS/RAF/MEK/ERK, the PI3K-AKT-mTOR, and TGFβ signaling converge on the activation of GLI1, promoting cellular proliferation, tumor progression, chemotherapeutic resistance, and early metastasis." (PMID 34113570, 2021). "Indeed, in pancreatic cancer Allenson and colleagues reported a higher detection rate of KRAS mutations in exoDNA than in cfDNA by droplet digital PCR7." (PMID 34811396, 2021). "Intriguingly, pancreatic cancers often exhibit KRAS mutation and constitutive activation." (PMID 33793053, 2021). "In view of the presence of KRAS mutations in most pancreatic cancers, whether PSCs enhance the Warburg effect through mutual regulation with KRAS mutations and ultimately lead to the carcinogenesis of CP is worthy of further study." (PMID 34540683, 2021). "In view of the therapeutic relevance of these fusions and the overall high incidence of oncogenic fusions in KRAS wild-type pancreatic tumors, we recommend systematic testing of the KRAS mutation status and screening for gene fusions in the absence of KRAS mutations." (PMID 33441414, 2021). "More studies are needed to elucidate the signaling pathway involved in STAT3-induced HPS expression and the HPS-mediated EPA/ACC-1 lipogenic axis in KRAS-mutant pancreatic tumors, and our study hereby proposes that HPS is a promising therapeutic strategy for KRAS-mutated-driven pancreatic cancer." (PMID 33801246, 2021). "Targeting KRAS mutations may give rise to potential treatment strategies for the unresolved problem of pancreatic cancer." (PMID 34638560, 2021). "The authors concluded that a KRAS mutation in FNA material from a pancreatic mass may help discriminate pancreatic cancer from inflammatory conditions such as AIP." (PMID 34573995, 2021). "KRAS mutation is a common driver mutation for several cancer types including pancreatic cancer." (PMID 34484187, 2021). "The ability of ZNF154 methylation to outperform KRAS mutations for the detection pancreatic cancer in patient plasma may reflect technical differences between the assays used and biological differences between DNA methylation and mutations." (PMID 33420235, 2021). "KRAS mutations are found in 90% of pancreatic cancer patients." (PMID 33793053, 2021). "Furthermore, deltarasin was shown to decrease proliferation and increase apoptosis in KRAS mutated pancreatic tumor cells through the blockage of PDEδ–KRAS interaction, thus preventing their membrane localization in these cells." (PMID 34638560, 2021).
pancreatic cancer (continued). "In addition, oncogenic KRAS mutations are commonly seen in most human pancreatic tumors and are associated with increased glucose and glutamate consumption to support anabolic processes, including nucleotide, lipid and nonessential amino acid biosynthesis." (PMID 34638256, 2021). "Activating KRAS mutations are most frequently observed in pancreatic cancer (88%)." (PMID 33544116, 2021). "Moreover, recently integrated whole-genome analysis uncovered that the molecular subtypes of pancreatic cancer are linked to specific copy number aberrations in genes such as mutant KRAS and GATA6." (PMID 34771630, 2021). "This may explain why several of the human pancreatic cancer cell lines that are commonly used in research carry two mutant KRAS alleles (e.g., AsPC-1, MIA PaCa-2, Capan-1, KP-3; source NCI RAS Initiative)." (PMID 34491463, 2021). "KRAS mutation is a major regulator in the tumor progression of pancreatic cancer." (PMID 34829828, 2021). "Ninety-five percent of patients with pancreatic cancer demonstrate KRAS molecule mutations." (PMID 34901697, 2021). "Most pancreatic cancer cells, including MiaPaCa2, have common activating point mutations in KRAS, leading to uncontrolled activation of downstream intracellular signalling pathways, including the RAF/MEK/ERK pathway, contributing to tumour cell proliferation and survival." (PMID 34824367, 2021). "Furthermore, studies have shown that MEK inhibitors did not improve overall survival in patients with advanced non-small cell lung cancer (NSCLC) or pancreatic cancer harboring KRAS mutations." (PMID 33982211, 2021). "As we all know, KRAS oncogene mutation was a switch of pancreatic cancer initiation, hence, above findings suggested that HSF1 may be a critical molecular for pancreatic cancer tumorigenesis again." (PMID 33422093, 2021). "Thereby, the methodology of integrating ctDNAs with KRAS mutation, methylation on targeted genes, and high expression level of tumor-specific proteins predominantly occupies a position in early diagnosis of pancreatic cancers." (PMID 34434889, 2021). "Likewise, digital droplet PCR has been used to measure EV-related KRAS mutant allele frequency (MAF) in NACT-treated pancreatic cancer, evidencing a decrease in KRAS MAF in responsive patients with no disease progression." (PMID 33670185, 2021). "The presence of a KRAS mutation highlights that SMC may represent another potential pancreatic cancer precursor." (PMID 33511431, 2021). "The collective results of this study demonstrated that gain-of-function mutations in KRAS play a crucial role in the initiation of pancreatic neoplasms, but mutant KRAS alone was insufficient to drive invasive characteristics of transforming acinar cells and their duct-like descendants." (PMID 34491463, 2021). "As a key modulator of pancreatic cancer, KRAS mutation is a potential therapeutic target." (PMID 33643376, 2021). "Thus, KRAS mutation is the main hurdle in pancreatic cancer treatment and is a major target for the development of therapeutic agents, as it affects tumor development, rapid progression, and drug resistance." (PMID 34829828, 2021). "Up to 90% of pancreatic cancers carry activating mutations in KRAS." (PMID 34439095, 2021). "Pancreatic cancer samples exhibited high frequencies of KRAS (62.8%) and CDKN2A (17.2%) mutations." (PMID 33397889, 2021). "KRAS mutations affecting codon 12 comprise of nearly all KRAS mutations in pancreas cancer." (PMID 33405090, 2021). "EPA supplements could potentially inhibit or reduce ACC-1-involved lipogenesis and HPS/FGL1-mediated cell survival in KRAS-mutated pancreatic cancer cells." (PMID 33801246, 2021).
pancreatic cancer (continued). "However, KRAS p.G12C mutation only occurred in a small fraction of pancreatic cancer, as evident in our cohort and the TCGA cohorts." (PMID 33350171, 2021). "RPs effect has been linked to KRAS, an oncogene mutated in 90% of pancreatic cancer." (PMID 34873618, 2021). "However, they showed that the concordance of KRAS mutation detection in resected primary pancreatic tumors was greater for exoDNA than cfDNA." (PMID 34811396, 2021). "With regard to pancreatic cancer, deletion of Ptf1a causes acinar to ductal metaplasia and dramatically enhances KRAS-driven acinar cell transformation in mice and downregulation is observed in human PDAC, leading to the postulation that PTF1A/p48 functions as a tumor suppressor gene." (PMID 34692545, 2021). "KRAS mutations occurred in the early stage of pancreatic cancer." (PMID 33747931, 2021). "Furthermore, pancreatic cancers have more than 90% KRAS mutation and KRAS is one of the most frequently mutated oncogenes of the RAS family, and it is reported that combinatorial therapies with TOR inhibitors will be necessary against RAS-driven cancers." (PMID 34685533, 2021). "This is of vital importance since 95% of primary pancreatic tumors show mutations in the KRAS gene." (PMID 34572731, 2021). "Interestingly while components of the EFR3A complex were upregulated in KRAS mutation-positive pancreatic tumors, we nevertheless show synergy of C7 with sotorasib in KRASG12C-mutant human lung adenocarcinoma cell lines." (PMID 34504076, 2021). "It is widely known that KRAS is mutated in about 90% of pancreatic cancer cases and contributes to cancer cell proliferation via the MAPK pathway and STAT3 activation; thus, many studies are now investigating ways to target STAT3 as a therapeutic intervention for KRAS-mutant pancreatic tumors." (PMID 33801246, 2021). "We performed a single-molecule high-resolution DNA melt analysis on 71 plasma samples from cancer patients and 20 noncancer individuals to assess ZNF154 methylation as a candidate diagnostic metric in liquid biopsy and compared results to KRAS mutation frequency in the case of pancreatic carcinoma." (PMID 33420235, 2021). "Likewise, KRAS mutations were highly prevalent in the pancreatic cancer cohort, a malignancy with an observed KRAS mutation rate of up to 95%." (PMID 33026356, 2020). "This protein panel could be used as a capture assay to enrich pancreatic cancer-specific exosomal cargo, which may improve detection of molecular alterations such as KRAS mutations." (PMID 32974169, 2020). "In addition, F-box and WD repeat domain-containing 7 (FBW7), a pancreatic tumor suppressor inhibited by oncogenic KRAS mutation, inhibited glycolysis in pancreatic cancer cells and enhanced the efficacy of gemcitabine in xenograft models as well." (PMID 32122374, 2020). "Moreover, KRAS mutation in Dclk1+ pancreatic epithelial cells leads to pancreatic cancer in the presence of induced pancreatitis." (PMID 33348546, 2020). "Our data indicate that newly developed MBD–ddPCR is a sensitive method to detect cfDNA methylation and that using five marker genes plus KRAS mutations may be useful for the detection of pancreatic cancers." (PMID 32520974, 2020). "In a prospective study in advanced pancreatic cancer, ctDNA was analyzed for KRAS mutations using blood samples collected prior to gemcitabine or FOLFIRINOX (5-fluorouracil, oxaliplatin, irinotecan, and leucovorin) treatment and monthly during treatment (median follow-up, 3.7 months)." (PMID 32010431, 2020). "In contrast to that in pancreatic cancer, the mutation rate of KRAS in liver cancer is very low." (PMID 32467562, 2020). "Moreover, the high rate of KRAS mutations in pancreatic cancer patients was confirmed by the other studies." (PMID 33127962, 2020).
pancreatic cancer (continued). "Hence, the analysis of KRAS mutations in cfDNA has been proposed as non-invasive surrogate for tissue biopsies in patients with pancreatic cancer." (PMID 32630266, 2020). "In pancreatic cancer, KRAS G12D driver mutation elevates glutamine-based NADPH synthesis." (PMID 33081387, 2020). "KRAS is the most frequently mutated oncogene in humans: more than 80% of pancreatic cancers and more than 30% of colorectal and cholangial cancers and lung adenocarcinomas harbor activating mutations of KRAS gene as one of the founder carcinogenic mutation in the genome." (PMID 32725342, 2020). "Interestingly, somatic ATM deficiency increases DNA damage in KRAS-mut precancerous lesions, transformed cells acquire new oncogenic mutations and pancreatic tumor is overt." (PMID 33266496, 2020). "Here, the authors establish a KRAS-driven mouse model of pancreatic cancer with conditional loss of AGO2 and show that the early phase of neoplastic lesion initiation is dependent on EGFR/RAS but not AGO2, while AGO2 is required for pancreatic ductal adenocarcinoma progression and metastasis." (PMID 32499547, 2020). "In more than 90% of pancreatic cancers, mutation of KRAS has been observed." (PMID 32690867, 2020). "Additionally, even in KRAS mutated pancreatic cancer cells, such as L3.6 cells, the inhibition of FGFR activity is still capable of reducing stemness." (PMID 32457900, 2020). "Notably, KRAS mutations are known to be the most frequently occurring mutations in pancreatic cancers." (PMID 32520974, 2020). "Therefore, a combination regimen that simultaneously targets the abnormal KRAS signaling pathway and the autophagic process in cancer cells is implicated as a novel and feasible treatment modality for pancreatic cancer patients." (PMID 32532955, 2020). "The diagnostic accuracy (sensitivity and specificity) of KRAS mutation testing was assessed across all included studies in an analysis that compared patients with pancreatic cancer with all other test subjects (pancreatitis, benign tumours and healthy patients)." (PMID 32825312, 2020). "Since our results indicate that KRAS suppression is associated with CpG methylation changes in pancreatic cancer cell lines, we hypothesized that the overexpression of oncogenic KRAS would also lead to DNA methylation changes." (PMID 32576853, 2020). "CTC lines exhibited KRAS mutations, consistent with pancreatic cancers." (PMID 32326109, 2020). "KRAS is known to be very commonly mutated driver gene (90%) in pancreatic cancer." (PMID 32552660, 2020). "Of 137 pancreatic cancers, 36, 59, and 42 were KRAS wild type, KRAS mutations, and of an unknown mutation status, respectively." (PMID 32520974, 2020). "However, the very different prognosis for the two tumors underlines that a mutated KRAS cannot explain the very bad prognosis for pancreatic tumors." (PMID 31990272, 2020). "More than 90% of pancreatic cancers contain a mutated KRAS gene." (PMID 31963309, 2020). "It has been reported that about 90% of the later stage pancreatic cancers have point mutations of KRAS, indicating that KRAS may be used as a diagnostic marker of PDAC." (PMID 33193628, 2020). "Collectively, these data suggest that miR181ab1 regulates a series of genes involved in the induction of the tumor phenotype whose expression associates with lung and pancreatic cancer patients’ survival, in line with its strong functional role in both types of mutant KRAS-driven cancers." (PMID 31874105, 2020). "KRAS is the most common target because approximately 90% of pancreatic cancer harbor KRAS mutation." (PMID 31470511, 2019).
pancreatic cancer (continued). "Of note, > 90% of the TCGA pancreatic cancers are KRAS-mutated." (PMID 31827798, 2019). "The KRAS gene is mutated in more than 90% of pancreatic cancer patients." (PMID 30863319, 2019). "Most of the pancreatic cancer cell lines have KRAS mutations." (PMID 31867280, 2019). "TB32047 is a murine pancreatic tumor cell line with a KRAS mutation." (PMID 31683647, 2019). "Future clinical trials testing MEK inhibitors in colorectal and pancreatic cancer could select patients possessing KRAS mutations to improve their chances of success." (PMID 31602313, 2019). "Pancreatic cancer cell growth is dependent on mutated KRAS activity." (PMID 31284594, 2019). "Furthermore, FBXW7 is significantly co-mutated with KRAS in colon cancer and ATM is significantly co-mutated with KRAS in pancreatic cancer." (PMID 31748650, 2019). "Current studies on PC showed that the total amount of circulating cfDNA and KRAS mutations in ctDNA might be associated with pancreatic tumor burden, but the conclusions remained inconsistent." (PMID 31850201, 2019). "Taken together, this raises the possibility that SEMA3C signalling may have a role in maintaining the oncogenic effects of KRAS mutations in pancreatic cancer." (PMID 30759745, 2019). "However, the clinical significance of KRAS-mutated ctDNA for pancreatic cancer has been inconsistent with respect to its prognostic and predictive potential." (PMID 31891652, 2019). "Pancreatic cancer exhibits a high frequency (75–95%) of KRAS mutations." (PMID 31383871, 2019). "In the present study, our results demonstrated that introduction of KRAS G12D mutation, a mutation frequently observed in pancreatic cancer, could increase Rad51 mRNA and protein expression levels." (PMID 31889908, 2019). "In pancreatic cancer, KRAS mutations are an early event being detectable in the initial lesions known as pancreatic intraepithelial neoplasias (PanIN), which can progress in infiltrating ductal carcinomas through the acquisition of additional genetic alterations." (PMID 31544066, 2019). "Activation of KRAS signaling has been linked to progression of pancreatic cancer." (PMID 30863319, 2019). "Therefore, KRAS codon 12 mutations in ctDNA represent an important potential biomarker of pancreatic cancer, which is fatal disease that is often diagnosed at advanced stages due to a lack of suitable techniques for early detection and diagnosis." (PMID 31383871, 2019). "ADAM17‐mediated shedding of EGFR family ligands has been linked to oncogenic KRAS‐induced pancreatic cancer, suggesting that other ADAM17 substrates may also contribute to mutant KRAS‐driven LAC." (PMID 30833304, 2019). "Pancreatic ductal adenocarcinoma with a mutant KRas gene is more susceptible to ferroptosis, and it might be related to the tumorigenesis of pancreatic carcinoma." (PMID 31367187, 2019). "We discuss here the presence of tumor-infiltrating B cells (TIB) in patients with pancreatic cancer that produce KRAS-mutant specific IgG, underlining that intratumoral T and B cells may exclusively target mutant KRAS." (PMID 30283732, 2018). "It is worth mentioning that the similar inhibition manner could be observed from other pancreatic cancer cell lines bearing KRas mutations, in support of the preferential survival inhibition effect on mutant cancer cell lines." (PMID 29467941, 2018).